CHRNA5 (cholinergic receptor nicotinic alpha 5 subunit)
Diseases named in the same sentence as CHRNA5 in open-access papers (continued):
Sharing a sentence is not in itself a finding about the gene and the disease.
lymph node metastasis (2 papers, 2018 to 2024). "In this study, nicotine-induced upregulation of CHRNA5 was found to promote the metastatic potential of LSCC cells in vitro and in vivo, and CHRNA5 was found to be significantly associated with lymph node metastasis and poor prognosis in patients with LSCC." (PMID 38879667, 2024). "In addition, CHRNA5 expression was higher among patients with lymph node metastasis (N+) than among those without lymph node invasion (N0) (p < 0.05)." (PMID 38879667, 2024).
Obesity (2 papers, 2014 to 2017). Accumulation of substantial excess body fat. "For example, after correction for multiple testing, no variant in CHRNA5 was individually associated with any of the examined obesity measures, but gene-based analysis showed that this gene was significantly associated with waist circumference." (PMID 25036316, 2014).
small cell lung carcinoma (2 papers, 2018 to 2019). Small cell lung cancer (SCLC) is a highly aggressive malignant neoplasm, accounting for 10-15% of lung cancer cases, characterized byrapid growth, and early metastasis. "It was also found that nAChR genes CHRNA3, CHRNA5, and CHRNB4 were necessary for the survival of small cell lung cancer (SCLC) and that α-conotoxin AuIB, a selective antagonist of α3β4 nAChR, inhibited the survival of SCLC cells." (PMID 31035425, 2019). "RNAi against CHRNA5 or STAT3 can lead to inhibition of cellular proliferation in NSCLC cell lines; and a mouse xenograft study shows that tumors derived from a CHRNA5-depleted small cell lung carcinoma cell line have lower size and weight in comparison to the controls." (PMID 30543688, 2018).
squamous cell lung carcinoma (2 papers, 2018 to 2020). A carcinoma arising from squamous bronchial epithelial cells. "Moreover depletion of CHRNA5 alters cell adhesion and activity of p63, an important molecule with established roles in cellular differentiation in squamous cell lung carcinoma where increased CHRNA5 levels are detected especially in smokers and in poorly differentiated tumors." (PMID 30543688, 2018).
Alzheimer disease (1 paper, 2024). A progressive, neurodegenerative disease characterized by loss of function and death of nerve cells in several areas of the brain leading to loss of cognitive function such as memory and language. "Taken together, these findings suggest that CHRNA5 and its nicotinic α5 subunit exert a neuroprotective role in aging and Alzheimer’s disease centered on chandelier interneurons." (PMID 38331937, 2024). "This combination suggests neuroprotective roles of CHRNA5 in β-amyloid pathology and makes CHRNA5 a target for therapies aiming to improve neuron survival in Alzheimer’s disease." (PMID 38331937, 2024). "Finally, we probed an estimated cell type proportion dataset from the PFC to assess the interaction effect of CHRNA5 SNPs and Alzheimer’s disease pathology on this CHRNA5-enriched cell type." (PMID 38331937, 2024). "Our findings suggest that CHRNA5 is involved in Alzheimer’s disease neuropathology." (PMID 38331937, 2024).
autism (1 paper, 2023). Persistent deficits in social interaction and communication and interaction as well as a markedly restricted repertoire of activity and interest as well as repetitive patterns of behavior. "Despite this, SNPs associated with CHRNA5 have been associated with a decrease in connectivity of a cortical output circuit linked with a cognitive profile that includes deficits in attention seen in autism." (PMID 37553252, 2023).
breast tumors (1 paper, 2018).
cholangiocarcinoma (1 paper, 2026). A carcinoma that arises from the intrahepatic biliary tree (intrahepatic cholangiocarcinoma) or from the junction, or adjacent to the junction, of the right and left hepatic ducts (hilar cholangiocarcinoma). "Our previous study demonstrated that the acetylcholine (Ach)/CHRNA5 axis promotes PNI progression in cholangiocarcinoma by upregulating BDNF expression through activation of the CAMKII/GSK3β/β‐catenin signaling pathway." (PMID 41556039, 2026).
colorectal cancer (1 paper, 2025). A primary or metastatic malignant neoplasm that affects the colon or rectum. "In colorectal cancer, high CHRNA3 expression was found to be associated with poor prognosis and to exhibit a strong physical interaction with CHRNA5." (PMID 41201200, 2025).
dementia (1 paper, 2024). Loss of intellectual abilities interfering with an individual's social and occupational functions. "To identify effects in aging and dementia of gene variants previously shown in younger adults to influence CHRNA5 expression and α5 coding, we examined brain expression quantitative trait loci (eQTL)." (PMID 38331937, 2024).
drug dependence (1 paper, 2013). "Because CHRNA5 has been shown to be a susceptibility locus for multiple substance dependence disorders, CA-induced methylation changes in CHRNA5 are potentially causally related to alcohol or drug dependence." (PMID 23799031, 2013).
esophageal cancer (1 paper, 2014). A primary or metastatic malignant neoplasm involving the esophagus. "It has been shown that CHRNA5 (neuronal acetylcholine receptor subunit alpha-5) and CHRNA3 (neuronal acetylcholine receptor subunit alpha-3) as negative regulators of nicotine signaling in bronchial cancer and esophageal cancer cells." (PMID 24621512, 2014).
Hypertension (1 paper, 2015). The presence of chronic increased pressure in the systemic arterial system. "However, little work has been done to determine whether the interaction between the CHRNA5-CHRNA3-CHRNB4 genotype and smoking quantity affects the risk of hypertension in Chinese smokers." (PMID 25874685, 2015).
hypopharyngeal carcinoma (1 paper, 2024). Carcinoma, predominantly squamous cell, arising from the epithelial cells of the hypopharynx. "Immunohistochemical staining revealed that the protein expression levels of CHRNA5 and Pan-ck in laryngocarcinoma and hypopharyngeal carcinoma were higher than those in the control group, with a significantly increased H-score (p < 0.05)." (PMID 39472448, 2024).
ischemic heart disease (1 paper, 2015). "However, the results of a cohort study indicate that the CHRNA5 rs1051730 polymorphism is not significantly linked with ischemic heart disease or ischemic stroke (RR = 0.9, 95% CI = 0.7–1.0; RR = 1.1, 95% CI = 0.8–1.4, respectively)." (PMID 25874685, 2015).
metastatic disease (1 paper, 2018). "Similarly, CHRNA5 and ASCL1 were differentially expressed in SCLC with the metastatic disease." (PMID 30364292, 2018).
nasal polyps (1 paper, 2021). "First, we analyzed samples of nasal polyps from 123 non-smoking patients with the three CHRNA5 genotypes at position 78590583 on GRCh38: wild-type (WT, G/G), heterozygous (HT, G/A), and homozygous (HO, A/A) for rs16969968 (α5SNP)." (PMID 34737286, 2021).
oral cancer (1 paper, 2019). "In this study, we further showed that nicotine exposure desensitizes oral cancer cells to irradiation treatment through the activation of CHRNA5-encoded neuronal nAChR." (PMID 31547418, 2019).
prostate carcinoma (1 paper, 2024). A carcinoma that arises from epithelial cells of the prostate gland. "CHRNA5 activates the AKT signalling pathway to promote the metastasis and proliferation of prostate cancer cells." (PMID 38879667, 2024).
psoriasis (1 paper, 2024). An autoimmune condition characterized by red, well-delineated plaques with silvery scales that are usually on the extensor surfaces and scalp. "We also found high expression of Chrna5 in patients with psoriasis in bulk RNA-seq of clinical samples." (PMID 38472183, 2024). "Our previous study showed that Chrna5 influences psoriasis-related inflammation and terminal skin differentiation." (PMID 38472183, 2024). "Moreover, knocking out Chrna5 significantly reduced the number of KCs in psoriasis, and EMT KCs were the main population that was obviously decreased." (PMID 38472183, 2024). "Therefore, the Chrna5 KO mouse model provides a good model to study the role of KCs in psoriasis." (PMID 38472183, 2024).
spinal muscular atrophy (1 paper, 2025). A motor neuron disease that affect the muscles, and characterized by muscle weakness and atrophy resulting from progressive degeneration and irreversible loss of the anterior horn cells in the spinal cord (i.e., lower motor neurons) and the brain stem nuclei. "While females retained two of the signals in the main analysis (CHRNA5 and IREB2), males had a single new signal related to a gene involved in spinal muscular atrophy (FGFBP3)." (PMID 40074595, 2025).
thyroid cancer (1 paper, 2025). "A database analysis revealed that among nAChR subunits, CHRNA5 was the most frequently upregulated in cancer tissues compared with normal tissues, including bladder, cervical, breast, uterine, lung, stomach, esophageal, colorectal, skin, brain, thyroid cancers, and others." (PMID 41201200, 2025).
tongue cancer (1 paper, 2025). A malignant neoplasm affecting the tongue. "The qRT‐PCR analysis revealed that CHRNA5 expression was highest, followed by CHRNA7 and then CHRNA3, in SCC‐4 tongue cancer cells." (PMID 41201200, 2025). "We integrated analyses of SCC‐4 tongue cancer cells with CHRNA overexpression, immunohistochemistry of OSCC pathological specimens, and data from the cancer genome atlas (TCGA), DepMap, and Puram 2017 to assess CHRNA3, CHRNA5, and CHRNA7 in OSCC/HNC." (PMID 41201200, 2025).
cancer (23 papers, 2012 to 2025). A tumor composed of atypical neoplastic, often pleomorphic cells that invade other tissues. "The results reveal that CHRNA5 is associated with many important cancer-related signaling pathways, such as cell cycle regulation, DNA replication, mismatch repair, and the Hippo signaling pathway in HCC." (PMID 35214008, 2022). "We found that higher CHRNA5 transcript levels are extensively detected in primary tumors compared to normal tissues and significantly predict an increased risk for cancer recurrence after radiotherapy in OSCC patients." (PMID 31547418, 2019). "Our microarray results reveal that knockdown of the CHRNA5 gene encoding α5-nAChR significantly modulates key pathways including the cell cycle, DNA replication, pathway in cancer." (PMID 28878681, 2017). "These associations are strongly localized to CHRNA5 in our African-American sample, and the cancer-associated risk alleles in CHRNA5 also influenced smoking behavior in our control population." (PMID 23232035, 2012). "For CHRNA5, a study has shown that knockdown of α5-nAChR, which is encoded by the CHRNA5 gene, could significantly mediate crux pathways, including cell cycle distribution, apoptosis, DNA replication and pathways in cancer." (PMID 31275410, 2019). "Furthermore, regarding recurrence-free survival, univariate and multivariate Cox regression analyses revealed that CHRNA5 is an independent prognostic marker with respect to other clinical risk factors that predict cancer recurrence in HNSCC patients." (PMID 31547418, 2019). "Among them CHRNA5 has been implicated in drug addiction as well as cancer development." (PMID 30543688, 2018). "Therefore, we hypothesize that SNPs within the CHRNA5-CHRNA3-CHRNB4 cluster could affect subjective cancer risk by altering receptor nicotine binding, normal cell proliferation, cell migration, and wound healing processes." (PMID 38834983, 2024). "Thus polymorphisms in CHRNA5-CHRNA3-CHRNB4 gene cluster may modulate the dynamics of the normal bronchial epithelium under stress conditions to influence cancer risks." (PMID 26981122, 2016). "It is suggested that SNPs in CHRNA5-CHRNA3-CHRNB4 clusters of neotenic acetylcholine receptor subunit genes could influence individual cancer susceptibility by altering receptor nicotine binding function, normal cell proliferation, cell migration and wound repair." (PMID 26079375, 2015). "Collectively, these results indicated that the switch to CHRNA5[AluSz] expression we observed in cancer would severely compromise the levels of canonical CHRNA5 that would otherwise be produced and, in turn, reduce the pro-tumour effects of CHRNA5 expression." (PMID 40336011, 2025). "As the most extensively investigated nAChR in cancer research, CHRNA5 has attracted widespread attention owing to its role in cancer metastasis." (PMID 38879667, 2024). "Gene set enrichment analysis demonstrated that the E2F signaling pathway is highly activated in OSCC tissues with high levels of CHRNA5 and in those derived from patients with cancer recurrence after radiotherapy." (PMID 31547418, 2019). "Increased CHRNA5 levels correlate with phosphorylated STAT3 levels in NSCLC implicating an important role for CHRNA5 in modulation of cellular signaling in cancer." (PMID 30543688, 2018). "We also test the genotype distributions and allele frequencies of CHRNA5 rs3841324 in the NPC cases and cancer-free controls." (PMID 25329654, 2014). "CHRNA5, a member of the ligand-gated ion channels, modulates cell membrane potentials and physiologic processes, including neurotransmission and cancer signaling." (PMID 25329654, 2014). "Consistent, with this notion, both the canonical and the CHRNA5[AluSz] isoforms were highly upregulated in several cancer types, compared with the respective normal tissues, with expression of the CHRNA5[AluSz] approaching or often exceeding that of the canonical isoform." (PMID 40336011, 2025).
cancer (continued). "Correlation analysis of immune cell infiltration revealed that CHRNA5 was significantly correlated with several cell types, including DC4+ T cells (Th1/2), cancer-associated fibroblasts, monocytes, mast cells, and M2 macrophages, as well as the microenvironment, stroma and immune score." (PMID 38840910, 2024). "Interestingly, several studies have highlighted CHRNA5’s dynamic role in nicotine sensitivity as well as its potential oncogenic role in different cancer types." (PMID 38371320, 2024). "Recently, several studies identified the critical role of CHRNA5 in several other cancers." (PMID 35214008, 2022). "For β4 nAChR, most studies have focused on the CHRNA5/CHRNA3/CHRNB4 cluster, wherein polymorphisms may be associated with an increased risk of death and incidence of cancer among smokers." (PMID 36284268, 2022). "The present literature further suggests that CHRNA5 may act as an oncogene possibly through its potential role in DNA damage response (DDR) as well as alteration of known cancer signaling pathways such as JAK/STAT, PI3K/AKT and Ras/Raf/MEK/ERK." (PMID 30543688, 2018). "Since CHRNA5 upregulation was indicated to be an independent risk factor for cancer recurrence in HNSCC, we next performed another Kaplan–Meier analysis to examine the association with cancer recurrence in HNSCC patients who were recorded to be receiving radiotherapy." (PMID 31547418, 2019). "Therefore, our analysis in HNSCC along with previous reports in other cancers associated with tobacco use highlight the potential importance of nicotinic receptor CHRNA5 in cancer progression and the potentially overlooked role nicotine induction via CHRNA5 may play in cancer severity." (PMID 38371320, 2024). "We found that CHRNA5 is crucial for the proliferation of HCC cells both in vitro and in vivo, consistent with the conclusion of previous studies in other types of cancers." (PMID 35214008, 2022). "To further test the prognostic value of high coexpression of CHRNA5 and CD274 in LUAD, we downloaded α5-nAChR and PD-L1 gene expression data from the cancer genomic browser of UCSC Xena." (PMID 35971127, 2022). "From these initial results, we then isolated TCGA HNSCC samples that had a tobacco smoking history (n=318) to further focus on the differential CHRNA5 expression status within this subset of HNSCC patients and postulate on its specific contribution in smoking-related HNSCC cancers." (PMID 38371320, 2024). "In addition, it is through the acetylcholine receptor pathway, which was composed of CHRNA5 and CHRNA3 in the 15q25.1 locus, that nicotine promote cancer cell proliferation, survival, migration, invasion, and tumor etiology and development." (PMID 25329654, 2014).